CGA (glycoprotein hormones, alpha polypeptide)
Diseases named in the same sentence as CGA in open-access papers (continued):
Sharing a sentence is not in itself a finding about the gene and the disease.
tumor (continued). "We next hypothesized that patients with a higher tumor load according to elevated Chromogranin A (CgA) concentrations might display further decrease in miR-223 concentrations." (PMID 33382770, 2020). "The mostly lobular pattern, Case 6 consisted of large oncocytic cells, which were strongly and diffusely stained for insulin but patchy and linear stained for CgA at 1% of tumor cell cytoplasm adjacent to the cell membrane and strongly and diffusely immunostained for SPY." (PMID 32020844, 2020). "Tumours stained strongly positive for both CgA and SSTR-2a in 18% of the cases (n = 30/163)." (PMID 31924180, 2020). "As these antibodies cannot cross-react with the cryptic PGPQLR site of full-length CgA, these data support the hypothesis that CgA cleavage at this site contributed to tumor growth." (PMID 33425767, 2020). "Age, WHO performance status of 2, an unknown primary tumour, Ki-67 index ≥ 10%, elevated CgA > 6x ULN, and elevated liver tests were identified as independent predictors for a worse DSS." (PMID 32756529, 2020). "Given these premises, the question arises as to whether CgA cleavage is just an epiphenomenon of tumor growth or whether it can affect tumor physiology." (PMID 33425767, 2020). "Considering that both cell types may represent a large component of the tumor tissues, their contribution to CgA degradation could also be relevant." (PMID 33425767, 2020). "In our population, in multivariable analysis age, a WHO performance status of 2, an unknown primary tumour, Ki-67 index ≥ 10%, elevated CgA > 6x ULN, and elevated liver tests were the strongest independent predictors for a worse DSS." (PMID 32756529, 2020). "Although macrophages and cancer-associated fibroblasts required much longer time than cancer cells to induce CgA cleavage, also these cells might significantly contribute to CgA cleavage in patients, given their considerable abundance in the tumor stroma." (PMID 33425767, 2020). "Many α-cells were arranged along the outer margin of the normal islet lobule, and Case 2 glucagonoma cells were weaker stained for glucagon than normal α-cells but moderately stained for CgA in 50% of individual tumor cell cytoplasm and diffusely and strongly for SPY." (PMID 32020844, 2020). "However, the prognostic value of CgA cleavage on tumor progression and patient survival still remains unexplored." (PMID 33425767, 2020). "The relationship between CgA and tumour load, however, remains debatable." (PMID 32778165, 2020). "The tumor was positive for CK+(CKLow), CgA(+), CD56(+), Syn(+), insulin(+), and β-catenin(+)." (PMID 32009878, 2019). "Increased levels of CgA could prove the presence of a neuroendocrine differentiation for some non-neuroendocrine carcinomas: This has been reported for several neoplasms, such as prostate cancer, small-cell lung cancer, breast cancer, colon-rectal cancer." (PMID 31382663, 2019). "In fact the lack of CT increase in case of disease recurrence makes it necessary to perform, in addition to CT, CEA and CgA evaluations, serial and close imaging tests, including neck US and CT, and MRI of liver and chest, even if the identification of small tumor is hard." (PMID 31142313, 2019). "However, the Italian investigator Angelo Corti reported that CgA regulates the formation of stroma in tumor tissues, promoting a shift of fibroblast phenotype and production of extracellular matrix proteins." (PMID 31480453, 2019). "Considering that the interaction between fragmented CgA and neuropilin‐1 is important for tumor growth, the PGPQLR site may be a potential therapeutic target." (PMID 31588572, 2019).
tumor (continued). "While tumor CgA expression negatively correlates with tumor size, serum CgA values showed a positive interrelationship with tumor size, presence of distant MTS and tumor stage, thus confirming literature data demonstrating an association of serum CgA values with tumor burden and patient outcome." (PMID 30867449, 2019). "CgA can be followed as a tumor marker if elevated at baseline, as was the case in our patient." (PMID 29696066, 2018). "The importance of tumor location on CgA production and cleavage was then investigated." (PMID 29723285, 2018). "IGF-1 is a factor essential for cell growth, proliferation and differentiation and preclinical studies in NET cell lines have demonstrated that over-expression of IGF-1 and/or IGF-1R, can induce tumor cell proliferation and raise Chromogranin A (CgA) synthesis." (PMID 29854305, 2018). "CgA correlated with age (rs = 0.388, p < 0.001) and tumor load (rs = 0.458, p < 0.001)." (PMID 30564197, 2018). "However, its accuracy as a tumor biomarker is relatively low because plasma CgA can increase also in patients with other diseases or in subjects treated with proton-pump inhibitors (PPIs), a class of widely-used drugs." (PMID 29723285, 2018). "The vast majority (>90%) of the tumor cells in the studied PCs expressed both CgA and Syn." (PMID 29854305, 2018). "In conclusion, the evaluation of serum CgA could be key in improving the management of CRPC patients displaying a mixed tumor form between adenocarcinoma and NEPC and treated with standard therapies." (PMID 30337589, 2018). "Thus the CgA was widely used in immunohistochemistry (IHC) to diagnose a benign or malignant tumor, and determine the tumor grade." (PMID 29728076, 2018). "A similar trend in the response pattern of the biochemical tumor markers CgA and 5HIAA was noted." (PMID 29167951, 2018). "Also for patients exhibiting a primary tumor localization in the pancreas or duodenum, a correlation of plasma CgA and tumor load has been reported." (PMID 29232390, 2017). "As the single determination of a tumor marker represents only a momentary view on the tumor, and levels of a tumor marker below a cut-off are possibly due to low tumor load, we evaluated plasma levels of CgA during follow up of patients with metastatic colorectal NEN." (PMID 29232390, 2017). "There was also a positive correlation between plasma levels of CgA and tumor burden." (PMID 29232390, 2017). "Moreover, except in one primary culture (tumor 2), CgA secretion was significantly decreased by 1nM octreotide." (PMID 28454119, 2017). "To assess whether CgA could regulate tumor angiogenesis, we investigated the effect of 30 and 150 pmol doses of recombinant CgA on tumor microvessel density by immunofluorescence microscopy in the WEHI-164 model." (PMID 27683038, 2016). "Although these findings suggest that CgA and some of its fragments might affect tumor biology, the pathophysiological relevance of circulating full-length CgA and the potential impact of CgA fragmentation on tumor progression remains to be established." (PMID 27683038, 2016). "Furthermore, we show that full-length CgA can impair angiogenesis, tumor perfusion and tumor growth through mechanisms depending on the induction of protease nexin-1, a serine protease inhibitor endowed of anti-angiogenic activity." (PMID 27683038, 2016). "To assess whether endogenous CgA, chronically produced and released in circulation by the neuroendocrine system, has a role in the regulation of tumor progression, we investigated the effect of CgA ablation on tumor growth in mice." (PMID 27683038, 2016). "What is the mechanism of the anti-tumor activity of full-length CgA?" (PMID 27683038, 2016). "A potential weakness of this study is that the number of patients used for evaluating whether changes in CgA levels were correlated with tumor response was relatively small." (PMID 27159453, 2016).
tumor (continued). "Except for a slightly increased serum chromogranin A (CgA) of 6.7 nmol/l (normal, <3.5 nmol/l), other tumor markers were normal including carcinoembryonic antigen (CEA) (2 μg/l; normal, <5 μg/l) and carbohydrate antigen 19–9 (CA 19–9) (5 kU/l; normal, <60 kU/l)." (PMID 27631424, 2016). "Notably, dose-escalation studies showed that CgA affects tumor growth with a U-shaped dose-response curve in all tumor models studied, with the maximal inhibitory activity being obtained with biweekly injections of 30 pmol of CgA (i.p.)." (PMID 27683038, 2016). "The mechanism of the anti-tumor activity of full-length CgA was then investigated." (PMID 27683038, 2016). "The mechanism of action of the anti-tumor activity of CgA was further investigated." (PMID 27203389, 2016). "Another possible explanation is that CgA levels were not only affected by tumor burden, they may also be affected by the tumor secreting activity." (PMID 27159453, 2016). "Immunoperoxidase staining for CgA and synaptophysin was positive in all tumor tissues." (PMID 26673010, 2016). "This view is supported by our observation that anti-PN1 antibodies could neutralize the anti-angiogenic activity of CgA in vitro as well as the anti-tumor activity of CgA in different in vivo models." (PMID 27683038, 2016). "This increase in CgA serum levels during ADT might reflect the development of increased tumor aggressiveness and CR." (PMID 25785244, 2015). "CgA and CgA-derived hormones also play opposing roles in regulating tumor proliferation." (PMID 25785244, 2015). "Upon immunohistochemical analysis, the tumor cells of MCC are labeled with neuroendocrine markers (CgA, Syn and NSE) and epithelial markers such as CK20 and CK8/18, which may show a characteristic perinuclear-dot pattern." (PMID 25663881, 2015). "Furthermore, in PCa patients, serum levels of CgA and NSE correlated with tumor stage, with a slightly higher resolution for CgA." (PMID 25785244, 2015). "A variety of prognostic factors has been described for patients with NETs including age, performance status, stage according to ENETS and AJCC, tumor load, levels of chromogranin A (CgA), presence of circulating tumor cells and grading based on the proliferation marker Ki-67." (PMID 26630134, 2015). "All G1/G2 tumours displayed strong immunoreactivity for CgA and synaptophysin." (PMID 24695372, 2014). "We have not found sufficient evidence to support SHLneuroendocrine origin, because the small amount of CgA and Synpositive cells might be the result of differentiation of tumor cells towards neuroendocrine cells." (PMID 25130377, 2014). "Focal CgA and Syn positive expression in polygonal tumor cells was observed in only one case." (PMID 25130377, 2014). "Circulating tumor transcripts were measured from the same samples (collected from 2008) as CgA." (PMID 25095873, 2014). "CgA was positively immunostained in the cytoplasm of tumor cells." (PMID 25501094, 2014). "Changes in CgA levels normalization or ≥30% decrease suggested that patients had tumor response." (PMID 25501094, 2014). "CgA expression was associated with tumor site and stage (P < 0.05), but not correlated with prognosis (P = 0.07)." (PMID 25501094, 2014). "One case was diagnosed as MANEC, expressing CgA and synaptophysin, tumour grade G3." (PMID 24695372, 2014). "Additionally, the CgA(+) and Syn(+) tumor cells were distributed differently from the NE cells in the normal mucosa." (PMID 25093184, 2014). "In our study, we observed that after different therapies including surgery, chemotherapy, somatostatin analogs therapy, and targeted therapy, normalization or ≥30% decrease in CgA levels suggested CR, PR, and SD, and <30% decrease or increase in CgA levels indicated tumor progression." (PMID 25501094, 2014). "The presence of CgA- and Syn-immunoreactive cells was evaluated in all tumor fields." (PMID 25093184, 2014).
tumor (continued). "To characterize the role of post-translational effectors, we evaluated mRNA and protein expression of the CgA processing enzyme prohormone convertase in both tumor tissue samples as well as cell lines and evaluated the effect of proliferation on CgA and this processing enzyme in vitro." (PMID 24260544, 2013). "Chromogranin A (CgA) is the most commonly used general tumor marker at the moment." (PMID 24282616, 2013). "Furthermore, physicians must be aware of poor prognostic indicators, such as large tumor size, advanced stage (≥T3), multifocal tumors, DNA ploidy, and CgA expression." (PMID 23627260, 2013). "In summary, the sensitivity of CgA as a tumor marker in neuroendocine tumors of the GEP system depends on the threshold cut-off level, on the specific assay for serum or plasma CgA determination, on NET primary location and on the spread of disease, especially the presence of liver metastases." (PMID 24213232, 2012). "CgA sensitivities (number of patients with median CgA values above reference range/number of all patients of the corresponding group) depending on hepatic metastatic spread and tumor primary." (PMID 24213232, 2012). "Recent findings implicating CgA could play important roles in tumor progression and response to therapy in cancer patients." (PMID 22529895, 2012). "FIGO stage, tumor mass size and CgA stained positive may act as a surrogate for factors prognostic of survival." (PMID 22529895, 2012). "In conclusion, the results of the present study demonstrate that FIGO stage, tumor mass size and CgA stained may act as surrogate for factors prognostic of survival." (PMID 22529895, 2012). "CgA sensitivities (number of patients with median CgA values above reference range/number of all patients of the corresponding group) depending on metastatic spread and tumor primary." (PMID 24213232, 2012). "We have therefore analyzed our single-center experience with CgA as tumor marker." (PMID 24213232, 2012). "In most cases tumor cells are immunohistochemically positive for CgA." (PMID 29147250, 2011). "In addition to tumor staging, we investigated the potential value of CgA serum levels for predicting treatment outcome." (PMID 19284605, 2009). "All tumours (19 out of 19) were strongly positive for CgA, with a granular cytoplasmic staining." (PMID 12771991, 2003). "The labelling pattern of NESP55, CgA and TH was compared in consecutive sections from some tumours." (PMID 12771991, 2003). "As ongoing research is readily concerned with tumor–immune cell interaction, looking into the relationship between CgA effectors and the direct immune microenvironment may be an important step to improve the understanding of regulatory mechanisms that limit immune response towards NEN." (PMID 39851539, 2025). "Some tumor cells may proliferate and metastasis independently of CgA related biological processes." (PMID 39975592, 2025). "Indeed, changes in CgA levels may reflect modifications in tumor activity and burden even before imaging studies show any changes." (PMID 38928704, 2024). "This classification defines breast NENs as a tumor entity characterized by epithelial‐derived tumors exhibiting morphological similarities to gastrointestinal and pulmonary neuroendocrine tumors (NETs), with over 50% of tumor cells expressing neuroendocrine markers (CgA and Syn)." (PMID 39585672, 2024). "Therefore, the combined use of CgA (a broad indicator of neuroendocrine cell activity and tumor burden) and SPP1 (associated with aggressive tumor behavior and metastasis) may provide additional benefits for the diagnosis of GEP-NENs." (PMID 38835066, 2024). "Indeed, CgA levels depend on the site of origin, with particularly high values for midgut carcinoids and pancreatic NENs, tumor burden, and secretory activity, with sensitivity and specificity ranging between 60–100% and 70–100% for different NENs, respectively." (PMID 38928704, 2024).
tumor (continued). "However, CgA correlates with tumor function, degree of differentiation, and extent of disease." (PMID 37685358, 2023). "However, as described in the current ENETS guidelines, an increase of more than 25% in the tumor marker chromogranin A (CgA) might be suggestive of disease progression and should give cause for CT, MRI, or SSR imaging anytime earlier." (PMID 38136263, 2023). "Additionally, CgA has a role as tumor surveillance marker after resection." (PMID 37077861, 2023). "Moreover, we validated the positive staining of CgA and Syn immunohistochemical markers, used in routine histopathological diagnostics, to confirm tumor categories of NENs and the positive staining of CgA and Calcitonin, specific immunohistochemical markers of MTC." (PMID 35794609, 2022). "The tumor aggressiveness of small NF PNENs could be predicted using CgA levels." (PMID 36615051, 2022). "The study showed that the differences in lymph node metastasis rate were statistically significance in age (p < 0.001), tumour size (p < 0.001), tumour location (p < 0.001), lymphovascular invasion (p < 0.001), muscularis propria invasion (p < 0.001), Ki 67 index (p < 0.001) and CgA (p < 0.001)." (PMID 34997303, 2022). "Human chromogranin A (CgA), a 439 residue-long member of the “granin” secretory protein family, is the precursor of several peptides and polypeptides involved in the regulation of the innate immunity, cardiovascular system, metabolism, angiogenesis, tissue repair, and tumor growth." (PMID 36559048, 2022). "Additionally, CgA showcases a greater utility in monitoring the progression of the disease and treatment response than as a diagnostic biomarker, as revealed by a 2018 meta-analysis on the subject, and increased values of CgA can predate radiological progression or tumor recurrence." (PMID 36233409, 2022). "Notably, aprotinin could also reduce the tumor growth rate (right), suggesting that CgA fragmentation contributed to tumor growth regulation." (PMID 33425767, 2020). "Thus, cleavage of circulating CgA in tumors and then in the blood may represent a complex mechanism for the spatio-temporal regulation of the tumor vascular biology." (PMID 33425767, 2020). "Thus, various kinds of cells potentially present in the tumor tissue may contribute, to a different extent, to CgA cleavage." (PMID 33425767, 2020). "In multivariable analysis age (HR 1.07), WHO performance status of 2 (HR 4.4), an unknown primary tumour (HR 3.2), Ki-67 index ≥ 10% (HR 12.6), CgA > 6 times ULN (HR 3.2) and elevated liver tests (HR 3.1) remained independent predictors for DSS in both the imputed as well as the non-imputed dataset." (PMID 32756529, 2020). "Notably, a significant correlation between tumor volume and CgA cleavage was observed in the Panc02 and BxPC3 models, possibly because large tumors could release more proteolytic enzymes." (PMID 33425767, 2020). "In the ENETS (European Neuroendocrine Tumor Society) guidelines, measurement of CgA is recommended during follow-up of patients diagnosed with NET since plasma concentrations are related to tumor burden and an increase in plasma concentration of CgA may be a predictor of disease progression." (PMID 33138020, 2020). "The following observations suggest that CgA cleavage may contribute to regulate tumor growth." (PMID 33425767, 2020). "Furthermore, one cannot exclude the possibility that the tumor‐derived CgA might be fragmented in a different manner, compared with CgA released in the blood by the neuroendocrine system." (PMID 31588572, 2019). "However, multivariate analysis (including IRS values of SSTs, CXCR4 and CgA, Ki-67 levels, patient age, tumor grade, size and stage, tumor functionality, presence of lymph node or distant MTS), revealed SST2A expression and Ki-67 levels as the only independent prognostic factors for patient outcome." (PMID 30867449, 2019).